SPRY3 (sprouty RTK signaling antagonist 3)
Description:
Inhibits neurite branching, arbor length and neurite complexity (By similarity). Inhibits EGF-mediated p42/44 ERK signaling (By similarity). Negatively regulates the MAPK cascade, resulting in a reduction of extracellular matrix protein accumulation. May function as an antagonist of fibroblast growth factor (FGF) pathways and may negatively modulate respiratory organogenesis.
Synonyms: Spry-3; HSPRY3
Tractability: No criterion of Open Targets' tractability assessment is met for any kind of drug.
Gene: Protein-coding gene on chromosome X (155,612,298 to 155,782,459, forward strand). Ensembl gene ENSG00000168939.
Subcellular location: Cytoplasm
Subcellular location (Human Protein Atlas): Cytosol; Nucleoli
Gene Ontology:
Molecular function: protein binding; protein kinase inhibitor activity
Biological process: negative regulation of MAPK cascade; negative regulation of epidermal growth factor receptor signaling pathway; negative regulation of ERK1 and ERK2 cascade; negative regulation of fibroblast growth factor receptor signaling pathway; negative regulation of neuron projection arborization; negative regulation of Ras protein signal transduction; regulation of signal transduction
Cellular component: cytoplasm; membrane
Homologues: Orthologues: chimpanzee SPRY3 (99% identical), macaque SPRY3 (99% identical), rabbit SPRY3 (98% identical), dog SPRY3 (98% identical), guinea pig SPRY3 (98% identical), pig SPRY3 (96% identical), rat Spry3 (82% identical), rat Spry3-ps1 (61% identical), tropical clawed frog spry3 (58% identical), Drosophila melanogaster sty (33% identical). Paralogues in human: SPRY2 (42% identical), SPRY1 (41% identical), SPRY4 (40% identical).
Diseases named in the same sentence as SPRY3 in open-access papers:
SPRY3 is named in the same sentence as 23 diseases in open-access papers, as found by Europe PMC text mining. Sharing a sentence is not in itself a finding about the gene and the disease. The quoted sentences say what the papers report.
glioblastoma (4 papers, 2019 to 2025). The most malignant astrocytic tumor (WHO grade IV). "In glioblastoma, Spry3 and Spry2 have a tumour-promoting potential, while Spry4 was shown to interfere with malignant features of glioblastoma." (PMID 40806483, 2025). "In the presented study we analyzed if Spry3 expression is a unique feature of glioblastoma and found that Spry3 is well expressed in osteosarcoma." (PMID 34769378, 2021). "In contrast, the role of Spry3 is only studied in glioblastoma, where it is like Spry2 functioning as tumor promoter." (PMID 34769378, 2021). "In the presented study, we investigated the expression of Spry3 and Spry4 in brain cancer-derived cells and analyzed how a modulation of their expression influences the behavior of glioblastoma-derived cell lines." (PMID 31374860, 2019). "Spry3 potentiates the tumorigenic potential of glioblastoma cells and Spry4 functions as tumor-suppressing protein in this entity." (PMID 31374860, 2019). "A similar function of Spry3 is already established in glioblastoma." (PMID 34769378, 2021). "However, SPRY3 is a designated tumour promoter for glioblastoma." (PMID 40867253, 2025). "In glioblastoma, for example, reduced signaling resulting in diminished pERK phosphorylation was observed as a result of Spry4 expression, but Spry3 exerted tumor-promoting activities without influencing these pathways." (PMID 34769378, 2021). "While Spry4 expression was mitogen-dependent and repressed in a number of cells from higher malignant brain cancers, Spry3 levels neither fluctuated in response to serum withdrawal nor were repressed in glioblastoma (GBM)-derived cell lines." (PMID 31374860, 2019).
autism (3 papers, 2019 to 2021). Persistent deficits in social interaction and communication and interaction as well as a markedly restricted repertoire of activity and interest as well as repetitive patterns of behavior. "On the contrary to our expectations, dog cfa6.7 that also maps in GALNT17, aligns with three different human genes (NRXN3, SLC9A7 and 15 kb upstream SPRY3) that are already involved in autism, two of which are X-linked." (PMID 34680999, 2021). "This makes the expression of the SPRY3 X-linked allele crucial and SPRY3 variants possible cohort of the male bias in autism prevalence." (PMID 34680999, 2021). "We previously analyzed the pseudoautosomal region 2 (PAR2)-linked SPRY3 gene in autism because it is highly expressed in the cerebellum, a region consistently implicated in autism pathogenesis." (PMID 31275178, 2019). "Data generated in Xenopus document that Spry3 is important in regulating axon branching of motoneurons, and the finding that Spry3 is associated with autism susceptibility indicates a further role in the human brain." (PMID 31374860, 2019). "We propose a pathogenic mechanism in autism involving SPRY3 deregulation impacting on the BDNF–TrkB–p75NTR neurotrophin pathway." (PMID 31275178, 2019). "The X-linked copy of SPRY3 is adjacent to a known autism gene, TMLHE, and a proportion of SPRY3 transcripts arise from upstream promoters in the X-linked F8A3 and TMLHE regions." (PMID 31275178, 2019). "As carnitine deficiency is implicated in autism causation, this suggests a mechanism whereby carnitine levels could impact on SPRY3 regulation and autism." (PMID 31275178, 2019). "Genetic and structural analysis of the Yq12 putative regulatory region was inconclusive; therefore, we looked for loss of epigenetic silencing and reactivation of the Y-linked SPRY3 allele in a comparison of RNA-Seq data from male autism and control cerebellum samples." (PMID 31275178, 2019). "SPRY3 is a receptor tyrosine kinase (RTK) signaling inhibitor that interacts with the TrkB neurotrophin receptor pathway, which is implicated in autism and social behavior." (PMID 31275178, 2019). "We have extended our previous work implicating SPRY3 in autism and provide evidence for a possible mechanism of chromosome Y-linked SPRY3 gene deregulation underpinning male susceptibility." (PMID 31275178, 2019). "In future work, we aim to deepen our understanding of SPRY3 and p75NTR expression and functional interactions during brain and lung development in the human and mouse, including in autism mouse models." (PMID 31275178, 2019). "We previously analyzed the regulation and expression of the pseudoautosomal region 2 gene SPRY3, which is adjacent to X chromosome-linked TMLHE, a known autism susceptibility gene." (PMID 31275178, 2019). "There are potentially two general mechanisms of SPRY3 deregulation in autism." (PMID 31275178, 2019). "More speculatively, SPRY3 deregulation could explain a reported, although currently unconfirmed, lung branching abnormality in autism." (PMID 31275178, 2019). "SPRY3 is expressed in Purkinje cells, a key cell type deficient in autism, but we note that mouse Spry3 is not expressed in the cerebellar lobules (VI–VII, X) homologous to those most affected in human autism." (PMID 31275178, 2019). "Spry3 is expressed in the mouse lung bronchial tree (our unpublished data) and in human lung (GTEx), suggesting that deregulation of SPRY3 could potentially provide a mechanism underpinning a lung branching abnormality reported in autism patients." (PMID 31275178, 2019). "In a screen of 135 genes in the adult mouse (selected for high cerebellar expression or prior association with autism), we identified only three (Abhd3, Lrp8, and Plcβ4) with a somewhat similar lobular expression pattern to Spry3, and none that recapitulated the p75NTR expression pattern." (PMID 31275178, 2019).
autism (continued). "Transgenic under- or over-expression of Spry3 in cerebellar lobules VI–VII and X in mice would provide an in vivo model of our proposed MDM in autism." (PMID 31275178, 2019). "We previously showed that mouse Spry3 is not expressed in cerebellar vermis lobules VI–VII and X, regions which exhibit significant Purkinje cell loss or abnormalities in autism." (PMID 31275178, 2019).
breast carcinoma (3 papers, 2011 to 2021). "Immunoblotting of logarithmically growing cells revealed that in contrast to breast cancer-derived cell lines, cells originated from osteosarcoma express prominent levels of Spry3 exceeding the ones observed in the brain cancer cell lines." (PMID 34769378, 2021). "Sprouty (Spry) family genes Spry1, Spry2 and Spry4 are differentially expressed in breast cancer, but Spry3 is rarely expressed." (PMID 31671542, 2019).
lung carcinoma (3 papers, 2017 to 2021). "In the tested lung cancer-derived cell lines the detected Spry3 levels were comparably low, while in colon cancer Spry3 was clearly detected in two of the three tested cell lines." (PMID 34769378, 2021). "Like Spry1 in lung cancer cells, Spry3 protein levels fail to fluctuate in response to serum-withdrawal in brain cancer-derived cells." (PMID 31374860, 2019). "This microRNA is capable of promoting lung cancer by subexpressing several regulators (SPRED1, SPRED2, SPRY1, RASA1, SPRY3 and SPRY4) in RAS / MAPK signaling, which leads to an increase in the signaling of this pathway." (PMID 29053755, 2017).
non-small cell lung carcinoma (3 papers, 2021 to 2024). A group of at least three distinct histological types of lung cancer, including non-small cell squamous cell carcinoma, adenocarcinoma, and large cell carcinoma. "In male non-small cell lung cancer cells, linc-SPRY3-2/3/4 has been found to interact with IGF2BP3, resulting in a decrease in the stability of specific IGF2BP3 binding mRNAs like anti-apoptotic HMGA2 mRNA and oncogenic c-MYC mRNA." (PMID 38760723, 2024). "In non-small cell lung cancer, lncRNA linc-SPRY3 could bind to IGF2BP3 (Insulin Like Growth Factor 2 MRNA Binding Protein 3), which leads to the destabilization of c-Myc and HMGA2, and improves the radiosensitivity of tumors." (PMID 35600868, 2022).
brain cancer (2 papers, 2019 to 2021). A primary or metastatic malignant neoplasm affecting the brain. "In the subsequent experiment, we determined the endogenous levels of Spry3 in different brain cancer-derived cell lines." (PMID 31374860, 2019). "To investigate if Spry3 and Spry4 interfere with cell proliferation in brain cancer-derived cells, we selected DBTRG-05MG and U373 cell lines to apply ectopic overexpression of the respective Spry proteins." (PMID 31374860, 2019). "First, we investigated if Spry3 expression is influenced by the grade of malignancy or the histological background of brain cancer-derived cells." (PMID 31374860, 2019). "Compared to control cells, doubling of shSpry3-treated cells was reduced from 0.58 to 0.50 doublings per day, substantiating an oncogenic effect of Spry3 in brain cancer." (PMID 31374860, 2019). "To evaluate if Spry3 is expressed in cancer cells originating from different tissues, we first compared Spry3 expression in cell lines derived from lung, bone, colon and breast tumors with the levels observed in brain cancer-derived cell lines." (PMID 34769378, 2021). "In summary, our study describes that Spry3 and Spry4 exert different roles in brain cancer." (PMID 31374860, 2019). "In this study we provide data showing that Spry3 and Spry4 expression may be altered in brain cancer and affect cell proliferation and migration in opposing ways." (PMID 31374860, 2019).
bone tumor (1 paper, 2021). "Corroborating the ability to fulfill a tumor-promoting function in osteosarcoma, Spry3 proteins are heavily overexpressed in this bone tumor-derived cancer, while it is hardly detectable in normal human osteoblasts." (PMID 34769378, 2021).
Ewing sarcoma (1 paper, 2021). A small round cell tumor that lacks morphologic, immunohistochemical, and electron microscopic evidence of neuroectodermal differentiation. "In malignant cells, Spry3 expression was not exclusively detected in the brain, since in accordance with our data in a recent publication, Spry3 was detected in Ewing’s sarcoma, another bone associated cancer." (PMID 34769378, 2021).
glioma (1 paper, 2025). A benign or malignant brain and spinal cord tumor that arises from glial cells (astrocytes, oligodendrocytes, ependymal cells). "SPRY3 protein levels are higher in GB cell lines than in cell lines from lower-grade glioma." (PMID 41516252, 2025). "The TCGA datasets concerning the effects of SPRY3 in GB are lacking, and the survival of adult glioma patients with low SPRY3 levels is non-significantly reduced." (PMID 41516252, 2025).
hypopituitarism (1 paper, 2025). A condition of diminution or cessation of secretion of one or more hormones from the anterior pituitary gland. "Aberrant FGF signaling caused by excessive SPRY3 activity can lead not only to structural anomalies, such as RCCs, but also to functional impairments, such as hypopituitarism." (PMID 41379151, 2025). "Investigating the potential molecular mechanisms underlying these associations, particularly the role of SPRY3 in pituitary gland development, may provide valuable insights for future studies on congenital hypopituitarism." (PMID 41379151, 2025).
osteosarcoma (1 paper, 2021). A usually aggressive malignant bone-forming mesenchymal neoplasm, predominantly affecting adolescents and young adults. "If a Spry3 protein is mutated to a version where the tyrosine in the N-terminal box is substituted by a phenylalanine mimicking a phosphorylation negative protein, its ectopic expression is able to inhibit cell migration of the osteosarcoma-derived U2OS cells." (PMID 34769378, 2021). "Along with the observations concerning Spry1, the herein presented data clearly demonstrate that Spry3 fulfills a tumor promoting function in osteosarcoma." (PMID 34769378, 2021). "The presented data show that osteosarcoma-derived cells express prominent levels of the Spry3 protein." (PMID 34769378, 2021). "The results of our studies revealed that high Spry3 levels enable more cells to grow anchorage-independently, corroborating that Spry3 expression is beneficial for the malignant phenotype of osteosarcoma." (PMID 34769378, 2021). "In contrast to U2OS cells, which express rather high Spry3 and low Spry1 levels, MG63 is the osteosarcoma-derived cell line with the highest Spry1 levels and has rather low Spry3 levels." (PMID 34769378, 2021). "Spry3 is hardly detectable in osteoblasts, while all osteosarcoma-derived cell lines show a prominent expression, although to a different extent." (PMID 34769378, 2021). "Both processes are important for establishing a tumor and therefore we can conclude that the malignant potential of osteosarcoma is increased by elevated Spry3 expression." (PMID 34769378, 2021). "Since the metastatic potential of osteosarcoma is crucial for patient’ prognosis, we additionally investigated how Spry3 is influencing the ability of the cells to form colonies in a semisolid medium." (PMID 34769378, 2021). "In combination with its promoting role on malignant processes in tumor cells these expression data confirm the oncogenic function of Spry3 in osteosarcoma." (PMID 34769378, 2021). "In the following experiments we characterized six osteosarcoma-derived cell lines concerning their relative expression levels of Spry3 and Spry1 and evaluated how mitogen availability is influencing these expression levels." (PMID 34769378, 2021). "U2OS cells express hardly detectable amounts of Spry1, while the Spry3 amounts are more pronounced than in the most other osteosarcoma-derived cell lines, but about five times less than in SAOS2 cells." (PMID 34769378, 2021). "Therefore, we first evaluated if elevated Spry1 and Spry3 levels are able to influence the cell proliferation of osteosarcoma-derived cells." (PMID 34769378, 2021). "All osteosarcoma-derived cell lines express Spry3 and Spry1, but wide variations were detected." (PMID 34769378, 2021). "Therefore, we investigated how ectopic Spry3 and Spry1 expressions influence the velocity of gap closure in a Scratch assay using osteosarcoma-derived cells." (PMID 34769378, 2021). "Furthermore, it is known that Spry2 exerts a strong tumor-suppressing activity in osteosarcoma, and Spry3 could interfere with this action." (PMID 34769378, 2021).
seminoma (1 paper, 2025). A radiosensitive malignant germ cell tumor found in the testis (especially undescended), and extragonadal sites (anterior mediastinum and pineal gland). "Notably, the most significant and common focal alteration targeted the pseudoautosomal region (PAR) at Xq28 in both subtypes (deleted in 38.5% of seminomas; 45% of non-seminomas), involving deletion of SPRY3, a potential negative regulator of the RAS/MAPK signaling pathway." (PMID 40568177, 2025).
tumor (9 papers, 2011 to 2025). "Pro-angiogenic miRNAs EBV-miR-BART10-5p and pro-metastatic hsa-miR-18a can be inhibited by their corresponding antagonists to slow tumour progression via downstream Spry3 pathway." (PMID 38473281, 2024). "To investigate if the tumor-promoting functions of Spry3 are dependent on the functional regulations conferred by this N-terminal box, we substituted the equivalent tyrosine at position 27 in Spry3 with a phenylalanine." (PMID 34769378, 2021). "Concomitant with the tumor-promoting impact, Spry3 expression enhances the amplitude of pERK signaling in response to serum." (PMID 34769378, 2021). "Their role is underscored by the accumulation of mutations in additional regulators of their activation during the course of this tumor's treatment: MAPK (SPRY3), PI3K (DEPDC5), and WNT (KREMEN2, NET1, GPR124)." (PMID 29440180, 2018). "This argues for a tumor-promoting function of Spry3 in GBMs." (PMID 31374860, 2019). "In NB, SPRY2 acts as a tumor suppressor, whereas the effects of SPRY1, -3, and -4 in NB have not been investigated so far, although the survival analysis revealed increased survival of NB patients with low SPRY3 levels in different datasets." (PMID 41516252, 2025). "Although an interaction of Spry3 with cCbl is not explicitly documented, interference with the degradation of a receptor could be another mode of action explaining the tumor-promoting activity of Spry3." (PMID 34769378, 2021).
cancer (3 papers, 2019 to 2023). A tumor composed of atypical neoplastic, often pleomorphic cells that invade other tissues. "With regard to Spry3, in normal brain tissue its expression is well documented, but due to its low abundance in other tissues, expression data in cancers are rarely available." (PMID 31374860, 2019). "Both these miRs promote cancer angiogenesis by downregulation of Spry3 expression." (PMID 37242569, 2023). "While Spry3 expression was on average elevated in cell lines originated from higher malignant tumors, Spry4 tended to be repressed in GBM and GS compared to cells derived from lower graded cancers." (PMID 31374860, 2019).
infection (2 papers, 2019 to 2021). The state of being infected such as from the introduction of a foreign agent such as serum, vaccine, antigenic substance or organism. "In U2OS as well as in MG63, both infection with Spry3 encoding and Spry1 harboring viruses results in a pronounced overexpression of the protein." (PMID 34769378, 2021). "Two days after infection, sufficient amounts of all Spry proteins were expressed, but the Spry3 antibody only detected Spry3." (PMID 31374860, 2019).
SPRY3 also shares sentences with these, for which no sentence is quoted: acute myeloid leukemia (1 paper); asthma (1); breast tumors (1); cardiac ischemia (1); colon cancer (1); hepatocellular carcinoma (1); liver cancer (1); myocardial infarction (1).